BDNF (brain derived neurotrophic factor)
Diseases named in the same sentence as BDNF in open-access papers (continued):
Sharing a sentence is not in itself a finding about the gene and the disease.
epilepsy (continued). "Existing reports on changes in BDNF levels in individuals with certain forms of epilepsy, both in the CNS and serum, are inconsistent." (PMID 38707431, 2024). "These outcomes excite many researchers to illustrate the link between BDNF and epilepsy by preclinical and clinical studies." (PMID 38006577, 2024). "The post hoc test revealed that the animals with epilepsy had a significantly lower BDNF expression in comparison with the C-veh group in the CA3 region of the hippocampus (p < 0.001)." (PMID 39727966, 2024). "This study was elaborated to assess the anticonvulsant and antiepileptogenic properties of an aqueous extract of Mimosa pudica in mouse model epilepsy: oxidative stress metabolism pathways, cholinergic, GABAergic, and BDNF signalling." (PMID 39996118, 2024). "In an in vivo model of epilepsy, the supplementation of brain-derived neurotropic factor (BDNF) and fibroblast growth factor-2 (FGF-2) using a Herpes-based vector reduced epileptogenesis-associated neuroinflammation." (PMID 38673746, 2024). "Some studies have demonstrated that higher serum BDNF levels are associated with an enhanced course of temporal lobe epilepsy (TLE) and other primary epilepsies." (PMID 38707431, 2024). "Using BDNF overexpression in cortical neurons of heterozygous Sip1 mice, it was possible to achieve 100% survival in the pilocarpine model of epilepsy." (PMID 39408863, 2024). "In this state, different studies indicated that dysregulation of brain-derived neurotrophic factor (BDNF) is concerned with the pathogenesis of epilepsy." (PMID 38006577, 2024). "BDNF-mediated activation of TrkB exerts different effects on epileptogenesis depending on the types of epilepsy model, natural history of experimental epilepsy, time of administration and TrkB inhibition or activation." (PMID 38006577, 2024). "In a mouse model of viral-induced epilepsy, the BDNF levels in the hippocampus increased, which led to a decrease in KCC2 followed by hyperexcitability and seizures." (PMID 39337430, 2024). "These abnormal FVB/N mice demonstrate the cardinal features of mouse models of epilepsy including spontaneous seizures, astrocytosis, neuronal hypertrophy, upregulation of brain-derived neurotrophic factor (BDNF), and sudden seizure-related death." (PMID 37199581, 2023). "Inhibiting neuronal apoptosis to prevent epilepsy appears to be possible with the activation of the AKT/CREB/BDNF signaling pathway." (PMID 37367679, 2023). "The average level of BDNF in serum that we detected herein (median = 3458.7 pg/mL) indicates an increased level of the analyte in the blood of patients with drug-resistant epilepsy." (PMID 38203674, 2023). "Metformin has shown promising utility in epilepsy management and epileptogenesis modulation by activating BDNF/TrkB signalling." (PMID 37737447, 2023). "In sum, these verdicts proposed that metformin attenuates epileptogenesis and epilepsy by indirect mechanisms mainly by modulating inflammatory and oxidative stress disorders, BDNF, α‐synuclein, mTOR pathway and neuroinflammation." (PMID 37737447, 2023). "A number of studies have demonstrated a dramatic increase in BDNF mRNA and protein expression in both animals and humans with epilepsy." (PMID 36677008, 2023). "Previous studies have reported that BDNF is increased in animal models and humans with epilepsy and involved in epileptogenesis." (PMID 37189441, 2023). "The conflicting research results regarding the effect of BDNF/TrkB signaling in epilepsy has led to further research in this area." (PMID 36831706, 2023). "The obtained data indicated that epilepsy favored migraine axis-mediated microglial activation in the cortex/thalamus/Sp5C accompanied by the BDNF release." (PMID 37569811, 2023).
epilepsy (continued). "The BDNF–TrkB signalling pathway is critical for the development of epilepsy, and nobiletin also inhibits seizures by inhibiting the BDNF–TrkB pathway." (PMID 37932838, 2023). "Activity-dependent BDNF expression is enriched in the hippocampus, which is a critical hub for social behaviors, memory, cognition and epilepsy, and is impaired in children with ASD and mouse models." (PMID 37205980, 2023). "It was also pointed out that there are currently too few confirmed studies to use BDNF as a marker for the development of epilepsy." (PMID 36831706, 2023). "We showed BDNF decrease both in BS and LF of epilepsy patients, while, on the contrary, CNTF in these media was increased." (PMID 38069144, 2023). "Seizure in temporal lobe epilepsy which is a severe and resistant form of epilepsy induces upregulation of BDNF/TrkB." (PMID 37737447, 2023). "There are conflicting reports of changes in BDNF levels in both CNS and serum in patients with certain forms of epilepsy." (PMID 36831706, 2023). "In our study, serum BDNF was reduces in both groups with epilepsy, PWE, and PWCED; in the PWMDD group, the decrease showed a statistically significant trend, the mean value being similar to that of two groups with epilepsy." (PMID 36142325, 2022). "The aim of the current study was to analyze the antiepileptic and analgesic effects of BDNF–TrkB signaling pathway in PAG of migraine comorbid epilepsy." (PMID 35557046, 2022). "Some authors assert that BDNF favors neuronal survival and growth in epileptic rats, whereas others agree that excessive expression of BDNF is involved in the pathogenesis of hippocampal hyperexcitability and epilepsy." (PMID 32929563, 2022). "Many studies have shown that BDNF participates in many nervous system diseases, including epilepsy and migraine." (PMID 35382731, 2022). "The activity was independent from CB1 modulation, and investigation on the expression of epilepsy-related genes showed the upregulation of mRNA coding for a variety of proteins, including the brain-derived neurotrophic factor (BDNF), only in responder animals." (PMID 36008978, 2022). "This discrepancy is most probably related to different role of BDNF in specific types of epilepsy and epileptogenesis and different expression and functions of BDNF in specific brain regions during the time course of epilepsy development." (PMID 36142325, 2022). "BDNF-TrkB receptor pathway, which plays a major role in triggering a series of downstream cascade reactions, is considered to be closely related with epilepsy." (PMID 35431921, 2022). "The role of BDNF in seizure development has been reported in some animal models of seizures and epilepsy, mostly electrical kindling, and post-status epilepticus (SE) models of TLE using kainic acid and pilocarpine." (PMID 35874836, 2022). "SIRT1 and BDNF have been identified as molecular targets of several miRNAs in the context of epilepsy." (PMID 35088379, 2022). "Several in vitro, ex vivo, and in vivo studies suggest an involvement of BDNF in the pathophysiology of epilepsy." (PMID 36142325, 2022). "Given its robust effects on neuronal development and differentiation, and synaptic plasticity, perturbations in the BDNF signaling has been reported in many neurological conditions including epilepsy." (PMID 35874836, 2022). "According to previous reports, BDNF plays an important role in the development of epilepsy and is closely related to neuronal survival and apoptosis, brain function and behavior, and synaptic plasticity." (PMID 35431921, 2022). "Further studies will focus on the effectiveness of AAV-Syn-BDNF-eGFP and AAV-Syn-GDNF-eGFP as therapeutic agents in provoking seizure activity in mutant mice with a genetic predisposition to epilepsy." (PMID 36009102, 2022).
epilepsy (continued). "BDNF is crucial in developing and maintaining neuronal populations within the central nervous system BDNF can be found in neurons, astrocytes, and microglia, which have a pivotal role in neuronal excitability in various conditions, including epilepsy." (PMID 36846103, 2022). "Neurotrophins and neurotrophin receptors, particularly BDNF and its receptor‐TrkB, lead to both epilepsy and migraine." (PMID 35557046, 2022). "Blood serum BDNF was significantly lower in patients with epilepsy (PWE, PWECD), while in the PWMDD group, the decrease showed a statistically significant trend (p = 0.055)." (PMID 36142325, 2022). "BDNF enhances neural sprouting, synaptic plasticity, and astrogliosis, thereby facilitating epileptogenesis, and elevated expression of BDNF and TrkB (BDNF receptor) has been reported in different animal models of epilepsy and in human patients with epilepsy." (PMID 34638578, 2021). "BDNF is closely related to epilepsy, since its upstream related genes and downstream receptors are found to be involved in the epileptogenesis." (PMID 34899313, 2021). "Most studies of PLCγ on epilepsy have focused on the BDNF/TrkB/PLCγ1 signaling cascade in epileptogenesis." (PMID 33808762, 2021). "Brain-derived neurotrophic factor (BDNF) and its receptor tropomyosin-related kinase B (TrkB) are involved in the pathophysiology observed with epilepsy." (PMID 33776649, 2021). "The use of BDNF gene polymorphism to replace the corresponding amino acid (Val66Met replaced by methionine) has a good therapeutic effect on epilepsy, while inhibiting the secretion of activity-dependent BDNF can prevent seizures." (PMID 34899313, 2021). "A wealth of studies have been done which show that mRNA of BDNF and its receptor Tropomyosin receptor kinase B (TrkB) are upregulated in epilepsy models, and have strong pro-epileptic effects." (PMID 33813634, 2021). "In a rat model of epilepsy, brain-derived neurotrophic factor (BDNF) levels were increased after playing Mozart's music." (PMID 34262520, 2021). "A related study demonstrated that GRIN2B, BDNF, and IL-1β gene significantly were upregulated and GRIN2B was positively correlated with the expressions of BDNF and IL-1β gene in people with epilepsy." (PMID 35069111, 2021). "Seizures also can upregulate protein levels of BDNF in the hippocampus and cortex in animal models of epilepsy." (PMID 35194435, 2021). "In an animal experiment, BDNF was also found to attenuate the decrease in the electrical potential of GABAergic neurons in the brain tissue of epilepsy model of rats." (PMID 34899313, 2021). "Conversely, increased BDNF concentration levels are observed in epilepsy; BDNF with its excitatory properties has a pro-epileptogenic effect." (PMID 34640441, 2021). "Studies have found that BDNF and its binding receptor, TrkB, are upregulated in animal models and that in patients with epilepsy, especially in the temporal and hippocampal regions." (PMID 35194435, 2021). "Therefore, it is speculated that BDNF may induce epilepsy by causing an increase in ROS production." (PMID 34899313, 2021). "BDNF and its receptor TrkB are both upregulated in epilepsy and their repression by REST seems to be an important regulatory switch to protect against epileptogenesis." (PMID 33813634, 2021). "Current evidence indicates that inhibiting the BDNF/TrkB pathway is a potential therapeutic strategy for epilepsy." (PMID 34425835, 2021). "Previous studies have shown that BDNF and TrkB molecules are very promising therapeutic targets for the treatment of epilepsy." (PMID 35194435, 2021). "In a rat model of epilepsy, kainic acid was found to increase BDNF protein in the cerebral cortex and hippocampus, which was attenuated by Rhy or Uncaria." (PMID 34207633, 2021). "In animal models and patients with epilepsy, both BDNF and TrkB are increased, and BDNF injected into the brain induces seizures." (PMID 34425835, 2021).
epilepsy (continued). "Studies have shown that BDNF and its receptor, TrκB, are upregulated following cerebral ischemia and epilepsy." (PMID 34212980, 2021). "A clinical study in patients with TLE showed that BDNF serum level in patients with TLE was significantly lower than that in the healthy controlsand the BDNF serum levels correlated with epilepsy duration." (PMID 34899313, 2021). "Evidence suggests a potential contribution of BDNF and its receptor, TrkB, in the pathophysiology of epilepsy." (PMID 34912196, 2021). "A previous study has shown that EE increases the level of BDNF protein by modulating BDNF gene expression in various brain disorders, including Huntington’s disease, epilepsy, traumatic brain injury, et cetera." (PMID 32581772, 2020). "In the context of epilepsy, indeed, most evidence indicates that BDNF increases neuronal excitability and contributes to epileptogenesis." (PMID 33396826, 2020). "Studies conducted in animal models of epilepsy observed an upregulation of BDNF immediately after experimentally induced seizures." (PMID 31915053, 2020). "The genetic associations of BDNF and NTRK2 with epilepsy have been studied, while their roles in epilepsy remain controversial and need to be verified." (PMID 33262686, 2020). "Conversely, in the periphery, decreased levels of plasma and serum BDNF have been reported in adult patients with epilepsy." (PMID 33584215, 2020). "For example, PVT1 was shown to act via the Wnt pathway to suppress astrocyte activation and induce BDNF expression in hippocampal tissues from epilepsy cases." (PMID 32404536, 2020). "Clinically, both BDNF and its receptor TrkB are elevated in patients with epilepsy, especially in the temporal and hippocampal area." (PMID 32267832, 2020). "Current evidence suggests that inhibiting BDNF–TrkB signaling represents a potential therapeutic strategy for epilepsy, especially for TLE." (PMID 32267832, 2020). "As an example, we will briefly discuss the effects of the A1R on the transcription factor nuclear factor-κB (NF-κB) and one of its target gene products—brain-derived neurotrophic factor (BDNF)—since these factors are involved in epilepsy." (PMID 33396826, 2020). "Serum BDNF is frequently higher in patients with epilepsy and appears to be positively correlated with severity of the disease." (PMID 32267832, 2020). "BDNF mRNA and protein are both markedly upregulated by seizure activity in the hippocampus of animal models of epilepsy as well as in human brain tissue displaying increased epileptic activities." (PMID 31581735, 2019). "Such is the case of the brain‐derived neurotrophic factor, BDNF (OMIM*113505), gene which is known to protect the carriers of the polymorphism p.Val66Met against early onset epilepsy (Li & Pozzo‐Miller, 2014)." (PMID 31206249, 2019). "Concerning epilepsy, a study found that the expression of BDNF is upregulated in human neocortex removed as a treatment of intractable seizures, whereas the levels of BDNF-AS are significantly decreased." (PMID 31581735, 2019). "Few studies have investigated the role of genes such as neuropeptide Y (NPY) gene, CREB1, and brain-derived neurotrophic factor (BDNF) that interact with each other to control epilepsy and enhance long term memory." (PMID 31708779, 2019). "Increased expression of miR-103a, GFAP, and number of apoptotic neurons, decreased expression of BDNF and number of surviving neurons were found in hippocampus tissues of epilepsy rats." (PMID 31049031, 2019). "For instance, BDNF level and activation of TrkB in hippocampal excitatory neurons were increased in animal models of epilepsy and human patients." (PMID 31780806, 2019). "Brain-derived neurotrophic factor (BDNF) is a neurotrophic factor that induces epilepsy both directly, as well as indirectly through the GABAergic and glutamatergic neurons." (PMID 31022879, 2019). "BDNF-TrkB signaling plays an important role in a variety of neuronal functions, and is involved in epilepsy." (PMID 31117204, 2019).
epilepsy (continued). "Our study provides evidence that the inhibition of miR-103a can inhibit the activation of astrocytes in hippocampus tissues and improve the pathological injury of neurons of epilepsy rats by regulating BDNF gene." (PMID 31049031, 2019). "The results demonstrated that inhibition of miR-103a can inhibit the activation of astrocytes in hippocampus tissues and improve the pathological injury of neurons of epilepsy rats through the targeted regulation of BDNF gene." (PMID 31049031, 2019). "The aim of this study is to explore the effect of microRNA-103a (miR-103a) on astrocytes activation and hippocampal neuron injury in epilepsy rats by targeting brain-derived neurotrophic factor (BDNF)." (PMID 31049031, 2019). "Recently, ultrapure amplicons produced using a highly defective helper virus have been employed to silence brain-derived neurotrophic factor (BDNF) expression in an animal model of epilepsy." (PMID 31312139, 2019). "One of the most important findings in this study revealed that upregulated miR-103a and downregulated BDNF are found in hippocampus of epilepsy rats." (PMID 31049031, 2019). "Based on which, this study is performed to explore the effects of miR-103a on astrocytes activation and hippocampal neuron injury in epilepsy rats by binding to BDNF." (PMID 31049031, 2019). "Altogether, these findings show a complex picture in which BDNF signaling can influence the pathogenicity of epilepsy both ways." (PMID 30210299, 2018). "The present study investigated the role of IGF-1 and BDNF in the regulation of autonomic functions and cerebral autoregulation in patients with epilepsy." (PMID 30524358, 2018). "In the present study, patient with epilepsy who have lower serum levels of BDNF showed impaired adrenergic and sudomotor function, and higher total scores of autonomic dysfunction, particularly in patients who have focal motor seizures." (PMID 30524358, 2018). "Since BDNF expression is augmented in neurons by various stressors (e.g., ischemia, epilepsy, hypoglycemia, and trauma), chronic exposure to BDNF confers neuroprotection." (PMID 30217051, 2018). "The present study provides novel insights into clinical observations regarding epilepsy by showing that reduced serum levels of BDNF and IGF-1, autonomic dysfunction, and impaired cerebral autoregulation are present in patients with focal epilepsy." (PMID 30524358, 2018). "Numerous studies showed that BDNF expression was up-regulated in various animal models of epilepsy and in human epileptic disorders." (PMID 30356026, 2018). "Since the expression of Kir4.1 channels is known to be down-regulated under certain disease conditions (e.g., epilepsy), we also evaluated the effects of Kir4.1 knockdown on astrocytic BDNF expression." (PMID 30356026, 2018). "Initial studies regarding the contribution of BDNF to epilepsy led to conflicting conclusions, with intrahippocampal BDNF perfusion or intraventricular injection of the BDNF scavenger TrkB-IgG, both being protective in a model of dorsal hippocampal kindling." (PMID 30210299, 2018). "Furin plays a crucial role as proprotein convertase, whose active substrates such as BDNF are closely related to epilepsy." (PMID 30333479, 2018). "Previous studies have demonstrated that BDNF levels are up-regulated in hippocampus of rat models with epilepsy, which can be down-regulated by delivery of VPT therapy." (PMID 29069823, 2017). "Specifically, the mRNA and protein levels of BDNF are known to be elevated in various animal models of epilepsy and in human epileptic brains." (PMID 29358904, 2017). "Given that the imbalance of inhibition and excitation is crucial to the development of epilepsy, these observations show that BDNF exerts modulatory control over both inhibitory and excitatory synaptic transmission in the brain." (PMID 27721996, 2016).